PMM1 (phosphomannomutase 1)
Description:
Involved in the synthesis of the GDP-mannose and dolichol-phosphate-mannose required for a number of critical mannosyl transfer reactions. In addition, may be responsible for the degradation of glucose-1,6-bisphosphate in ischemic brain.
Synonyms: PMM 1; Sec53; PMMH-22
Tractability: Small molecule: a structure with a bound ligand is known; it has a binding pocket of medium quality. PROTAC: ubiquitination databases record sites on it; its protein half-life has been measured.
Gene: Protein-coding gene on chromosome 22 (41,576,896 to 41,595,275, reverse strand). Ensembl gene ENSG00000100417.
Subcellular location: Cytoplasm
Subcellular location (Human Protein Atlas): Cytosol
Pathways (Reactome):
Metabolism of proteins: Synthesis of GDP-mannose
Gene Ontology:
Molecular function: phosphomannomutase activity; protein binding
Biological process: mannose metabolic process; GDP-mannose biosynthetic process; protein N-linked glycosylation
Cellular component: cytosol; cytoplasm; neuronal cell body
Genetic constraint (gnomAD): Loss-of-function variants: 23 observed, 30.54 expected, observed/expected ratio (o/e) 0.75, 90% interval 0.54 to 1.07. The upper end of that interval is the gene's LOEUF score, 1.07, which puts it in group 4 of 6, group 1 being the genes least tolerant of losing a copy. Missense variants: 311 observed, 351.29 expected, observed/expected ratio (o/e) 0.89, 90% interval 0.81 to 0.97. Synonymous variants: 133 observed, 145.57 expected, observed/expected ratio (o/e) 0.91, 90% interval 0.79 to 1.05.
Homologues: Orthologues: chimpanzee PMM1 (100% identical), dog PMM1 (97% identical), rabbit PMM1 (97% identical), pig PMM1 (96% identical), guinea pig PMM1 (95% identical), mouse Pmm1 (95% identical), rat Pmm1 (95% identical), tropical clawed frog pmm2 (75% identical), macaque PMM1 (58% identical), zebrafish pmm1 (55% identical), Caenorhabditis elegans F52B11.2 (52% identical), Drosophila melanogaster Pmm2 (50% identical). Paralogues in human: PMM2 (64% identical).
Diseases named in the same sentence as PMM1 in open-access papers:
PMM1 is named in the same sentence as 14 diseases in open-access papers, as found by Europe PMC text mining. Sharing a sentence is not in itself a finding about the gene and the disease. The quoted sentences say what the papers report.
asthma (2 papers, 2020 to 2021). "Finally, SNPs that were molecular QTLs in our study colocalized with asthma GWAS SNPs, revealing 46 unique colocalizations that included both known asthma loci (e.g., 17q12-21 and TSLP) and loci that did not meet stringent criteria for genome-wide significance in the GWASs (e.g., IRF5 and PMM1)." (PMID 34629083, 2021).
breast carcinoma (1 paper, 2022). "Expressed gene PMM1, located on chromosome bands, helps differentiate gene expression before and after radiation of subcutaneous fibroblasts, identifying breast cancer patients resistant to radiation-induced fibrosis." (PMID 35057823, 2022).
breast tumors (1 paper, 2006). "An investigation of different housekeeping genes revealed two independent genes, PMM1 and RPL32, suitable for mRNA expression level determination in human breast tumors." (PMID 17054774, 2006).
congenital disorder of glycosylation (1 paper, 2013). Congenital disorder of glycosylation (CDG) is a fast growing group of inborn errors of metabolism characterized by defective activity of enzymes that participate in glycosylation (modification of proteins and other macromolecules by adding and processing of oligosaccharide side chains). "The most common congenital glycosylation disorder (CGD) is in fact PMM2 deficiency (PMM2-CDG, MIM#212065), which was formerly known as Congenital Disorder of Glycosylation-Ia, CDG-Ia, or Jaeken syndrome; no CDG described so far is linked to mutations of PMM1." (PMID 24498599, 2013).
melanoma (1 paper, 2011). A malignant, usually aggressive tumor composed of atypical, neoplastic melanocytes. "The tumor size in the P. acnes-treated melanoma-bearing mice, PMM1 and PMM2, was significantly smaller than in the control mice." (PMID 22216160, 2011).
rectal cancer (1 paper, 2020). A primary or metastatic malignant neoplasm that affects the rectum. "The genes evaluated for rectal cancer and normal rectal samples in our study included GAPDH, RPNI, PUM1, B2M, and PMM1, which are involved in the process of transcription/translation; other genes are involved in nucleotide metabolism, are a part of the cytoskeleton, etc.." (PMID 33457124, 2020).
rectal tumors (1 paper, 2020). "Five promising reference genes GAPDH, Pumilio RNA binding family member 1 (PUM1), beta-2-microglobulin (B2M), ribophorin I (RPN1), and phosphomannomutase 1 (PMM1) were selected from different publications to assess their expression stability in rectal tumors as part of the screening phase." (PMID 33457124, 2020).
type 2 diabetes (1 paper, 2025). "PMM1 is an enzyme involved in the synthesis of GDP-mannose, and plasma mannose levels are related to incident type 2 diabetes and cardiovascular disease." (PMID 41301179, 2025).
PMM1 also shares sentences with these, for which no sentence is quoted: tumor (2 papers); cancer (1); cardiovascular disease (1); childhood onset asthma (1); disorder of glycosylation (1); neurodevelopmental disorder (1).